RNU6-990P (RNA, U6 small nuclear 990, pseudogene)
Gene: Small nuclear RNA gene on chromosome 17 (30,360,463 to 30,360,566, forward strand). Ensembl gene ENSG00000201255.
Homologues: Orthologues: chimpanzee U6 (99% identical), macaque U6 (93% identical), dog U6 (83% identical), pig U6 (78% identical), dog U6 (76% identical). Paralogues in human: RNU6-1316P (88% identical), RNU6-140P (87% identical), RNU6-40P (87% identical), RNU6-41P (87% identical), RNU6-44P (87% identical), RNU6-950P (87% identical), RNU6-1060P (86% identical), RNU6-1075P (86% identical), RNU6-1124P (86% identical), RNU6-116P (86% identical), RNU6-12P (86% identical), RNU6-13P (86% identical), and 1290 more.